VEGFA (vascular endothelial growth factor A)
Diseases named in the same sentence as VEGFA in open-access papers (continued):
Sharing a sentence is not in itself a finding about the gene and the disease.
breast cancer (continued). "Baseline plasma VEGFA measured in advanced breast cancer patients before treatment with bevacizumab and vinorelbine showed that patients who had lower baseline plasma VEGFA had longer time to progress (9.3 months in patients with VEGFA ≤32.6 pg/mL vs. 3.7 months in patients with VEGFA >32.6 pg/mL)." (PMID 23203097, 2012). "miR-138-5p inhibits HIF-1α/VEGFA signaling and vascular mimicry in hepatocellular carcinoma and suppresses EMT/migration in breast cancer, indicating its anti-angiogenic role in multiple contexts." (PMID 41516402, 2026). "In a humanized breast cancer mouse model, LSD1 inhibition resulted in reduced FLI1 target gene signatures related to angiogenesis (VEGFA, FGF-1, MMP-1, MMP-9), migration, and invasion (PLAU)." (PMID 41300765, 2025). "In oncology, its identification of spatially resolved therapeutic targets—such as VEGFA and CD74 in glioblastoma, or ARL2 and TMEM145 in breast cancer—highlights its potential to uncover microenvironment-specific drivers of disease progression." (PMID 41275376, 2025). "The polarized M2 macrophages secrete vascular endothelial growth factor (VEGFA) and immunosuppressive factors such as interleukin-10 (IL-10), thereby remodeling the pulmonary PMN and facilitating breast cancer cell colonization in the lung." (PMID 40564894, 2025). "In the process of PCD patterns affecting the prognosis of breast cancer, besides immune response, ALK, VEGFA/VEGFR2, NF-κB, HIF-1, PI3K-Akt, MAPK, and JAK-STAT signaling pathways played an important role." (PMID 40281780, 2025). "TNF and VEGFA are more commonly seen in studies of drugs that promote and inhibit sex hormone secretion, and EGFR inhibits gonadal axis secretion in breast cancer patients." (PMID 40238841, 2025). "CoQ10 inhibits the protein expression of VEGFA/VEGFR2 and then prevents the progression of breast cancer." (PMID 38687357, 2024). "For example, in breast cancer cells, lncRNA RAB11B-AS1 promotes VEGFA and ANGPTL4 gene transcription by recruiting RNA Pol II to their promoter, enhancing tumor angiogenesis." (PMID 38254660, 2024). "Vascular endothelial growth factor A (VEGFA) was the top potential target identified by our prioritization algorithm, which has already been approved for certain indications, including breast cancer." (PMID 39057065, 2024). "For example, shERα cells have been observed to markedly diminish the expression of angiogenic molecular markers, including vascular endothelial growth factor A (VEGF-A) and angiopoietin-2 (Ang-2), in breast cancer cells." (PMID 39194700, 2024). "The mRNA expression levels for eight pro-angiogenic genes [VEGFA, HGF, FGF1, FGF2, ANGPT1, ANGPT2, PDGFA, and PDGFB] were obtained from the METABRIC (Molecular Taxonomy of Breast Cancer International Consortium) dataset available at cBioPortal public domain." (PMID 39302921, 2024). "Exosomal miRNA-21 promotes the formation of osteolytic metastatic lesions in breast cancer, and exosomal mRNA of miRNA-19a, HSP90AA1, SPP1, IL3, VEGFA, and PTK2 genes have also been validated as biomarkers." (PMID 38041134, 2023). "Vascular endothelial growth factor A (VEGFA), a leading simulator of tumor-initiated angiogenesis, has been found to be overexpressed in many cancers, such as breast cancer, lung cancer, and colon cancer." (PMID 37239383, 2023). "ELISA assay also confirmed that VEGFA concentration was significantly downregulated in TCM from breast cancer cells of LAMP2A low expression and upregulated in TCM from breast cancer cells of LAMP2A overexpression." (PMID 36913368, 2023). "The present study provides a new link between CMA and angiogenesis, we show that CMA promotes VEGFA expression via regulation of HK2-mediated aerobic glycolysis, thus enhancing breast cancer angiogenesis." (PMID 36913368, 2023).
breast cancer (continued). "Another study showed that cytotoxic chemotherapy induced cellular senescence in hematopoietic tissues of breast cancer patients and prolonged the increase in SASP factors VEGFA and CCL2 levels." (PMID 37251343, 2023). "In breast cancer, miR-675-upregulated NEDD4L can catalyze the ubiquitination of PI3KCA, thereby inhibiting VEGFA secretion and ultimately inhibiting blood vessel formation." (PMID 38027016, 2023). "In breast cancer cells, ACE2 expression reduced cell migration and human umbilical vascular endothelial cell proliferation, and downregulated the expression of VEGFa." (PMID 37568724, 2023). "In breast cancer, the combination of E2F8 and hypoxia-inducible factor 1 (HIF1) has been shown to promote angiogenesis by inducing the expression of vascular endothelial growth factor A (VEGFA)." (PMID 36814821, 2023). "For example, recent study revealed that SerRS repressed the transcription of vascular endothelial growth factor A (VEGFA), inhibiting angiogenesis of breast cancer." (PMID 36698945, 2022). "Only high expression of two genes, including VEGFA and EZH2, indicated unfavorable overall survival of breast cancer patients." (PMID 35812757, 2022). "Increased METTL14 and ALKBH5 levels were detected in hypoxia-treated breast cancer cells, which led to upregulation of angiogenic transcripts, including TGF-β, matrix metallopeptidase 9 (MMP9), PDGF, and VEGFA." (PMID 36291060, 2022). "In breast cancer cells, zinc finger E-box binding homeobox 1 (ZEB1) activated VEGFA transcription through enhancing SP1 recruitment to VEGFA promoter." (PMID 36467048, 2022). "RAB11B-AS1 enhances hypoxia-induced VEGFA and ANGPTL4 expression in breast cancer and promotes angiogenesis and distant breast cancer metastasis in mice." (PMID 36139678, 2022). "High VEGFA and VEGFR expression in breast cancer patients correlates with worse outcomes and resistance to systemic therapy." (PMID 36074318, 2022). "This transcription factor can upregulate vascular endothelial growth factor-A (VEGF-A), VEGF-C, CD24, and CD44, leading to increased angiogenic potential, growth, migration and invasion of breast cancer cells." (PMID 35884845, 2022). "For example, HHEX inhibits cell proliferation through transcriptional repression of the VEGF signaling pathway components (VEGFA, VEGFR1, and VEGFR2) in leukemic K562 cells, breast cancer MCF7 cells, and HUVECs10,11,13." (PMID 36008411, 2022). "Another study confirmed the direct interaction between VEGFA and SP1 in breast cancer cells by Chromatin Immunoprecipitation (ChIP) experiment." (PMID 36467048, 2022). "They found that YTHDF3 promoted the binding between eukaryotic initiation factor 3 and angiogenic transcripts, such as VEGFA and epidermal growth factor receptor (EGFR), indicating its potential role as a therapeutic target in breast cancer." (PMID 36291060, 2022). "Here, we determined that the level of S1PR1 in breast cancer cells is positively correlated with STAT3 activation and VEGFA expression." (PMID 34059068, 2021). "NFIB overexpression discriminated between metastatic versus non‐metastatic TNBC breast cancer patient‐derived xenograft (PDX) models and NFIB, ERO1A and VEGFA were co‐overexpressed in these samples." (PMID 33751828, 2021). "We have also evaluated, in the same experimental conditions as above, the expression level of VEGFA isoforms, which we have previously reported to be affected by MALAT1 subnuclear localization in breast cancer cells." (PMID 34530916, 2021). "MiRNA-26, which targets both VEGFA and PIK3R2, plays a significant role in angiogenesis in human breast cancer, and its expression was decreased." (PMID 34778378, 2021). "The mRNA levels of EPAS1 as well as TGFB1, VEGFA and CA9, were confirmed to be positively correlated with those of SIPA1 in these two pairs of breast cancer cells and BT549, another TNBC cell line." (PMID 35096814, 2021).
breast cancer (continued). "Bevacizumab (Avastin), a monoclonal antibody directly targeting vascular endothelial growth factor-A (VEGF-A), has been widely used in clinical trials for patients with melanoma, HER2-negative breast cancer, and so on." (PMID 34439274, 2021). "Taken together, these data indicate that NFIB is a breast cancer metastasis transcriptional regulator which, through increased expression of ERO1A and VEGFA, promotes angiogenesis at the metastatic site." (PMID 33751828, 2021). "Increased VEGFA and CD31 expression was further detected in xenografts infected with PCDHB17 overexpression breast cancer cells." (PMID 34350110, 2021). "We have shown that miR526b and miR655 overexpression in breast cancer cells promotes EMT, cell migration, as well as VEGFA upregulation." (PMID 32707933, 2020). "VEGFA and FGF2 are two oncogenic growth factors overexpressed in many cancers including breast cancer." (PMID 32854238, 2020). "Yang and coworkers reported that ~10 nm AgNPs induced dose-dependent apoptosis in breast cancer cells but also inhibited the transcription of hypoxia-inducible factor-1 (HIF-1) and the induction of vascular endothelial growth factor-A (VEGF)." (PMID 33238486, 2020). "In breast cancer cells, lncRNA RAB11B-AS1 recruits RNA polymerase II to upregulate VEGFA and ANGPTL4 expression and promotes tumor angiogenesis." (PMID 32993787, 2020). "In human breast carcinoma MCF7 cells, overexpression of MMP-14 significantly increased the transcriptional expression of vascular endothelial growth factor A (VEGF-A)." (PMID 33352765, 2020). "To investigate new therapeutic strategies for treatment-resistant breast cancer, we explored treatment targets using multigene panels, which showed high expression of HIF1A, RAF1, AKT2 and VEGFA in two TNBC cases." (PMID 31018595, 2019). "(d-f) Kaplan Meier curves of RFS in a cohort of breast cancer patients stratified by HMGA1 (d), FOXM1 (e) and VEGFA (f) expression." (PMID 31311575, 2019). "In human breast cancer BT474 cells, VEGFA, HIF and EMCV IRESs are all activated after 24 hr of hypoxia." (PMID 31815666, 2019). "We then calculated the rank of the hub genes using the STRING database and the Cytoscape tool cytoHubba and identified VEGFa as the most plausible mediator of ACE2 and the inhibition of breast cancer angiogenesis." (PMID 31023337, 2019). "In the present study, we analysed the role of ACE2 in breast cancer prognosis using databases and human tissues, verified the anti-angiogenetic effects of ACE2 in vitro and in vivo and then revealed the VEGFa/VEGFR2/ERK pathway." (PMID 31023337, 2019). "In this study, the investigation from real-time quantitative PCR revealed that miRNA-16-5p was downregulated in breast carcinoma tissues and cells, coupled with the elevations of HIF-α and VEGFA protein expressions, compared with normal tissues." (PMID 29069797, 2017). "Meta-analysis revealed that human breast carcinomas express elevated levels of Fibronectin (FN1) and VEGFA compared to normal tissues." (PMID 28977919, 2017). "Adding VEGFA and FGF2 exogenously to chemosensitive breast cancer cells and chemoresistant cells with miR-205 overexpression led to drug resistance." (PMID 27362808, 2016). "In breast cancer, miRNA-205 targets VEGF-A (vascular endothelial growth factor A) which plays an important role in cancer metastasis." (PMID 27737015, 2016). "miR-126-3p is involved with the VEGF/PI3K/AKT signaling pathway and targets both VEGFA and PIK3R2, playing a role in vasculogenesis and tumor growth in human breast cancer." (PMID 27191494, 2016).
breast cancer (continued). "Here, the authors show that obesity promotes breast cancer through the recruitment of macrophages with activated NLRC4 inflammasome, which activate IL-1β production, resulting in VEGFA expression in adipocytes and angiogenesis." (PMID 27708283, 2016). "In breast cancer tissues, expression of ZEB1 was positively correlated with those of VEGFA and CD31." (PMID 26882471, 2016). "Altogether, these data strongly support a tumor-suppressor role and promoter of chemosensitivity for miR-205 by repression of VEGFA and FGF2 and enhancing cell apoptosis in breast cancer." (PMID 27362808, 2016). "We further performed a search using the transcription factor database TRANSFAC and identified 4 SP1 sites at positions -96/-88, -85/-77, -74/-66, and -60/-52 on the VEGFA promoter, which have been reported to mediate VEGF promoter activation in breast cancer." (PMID 26882471, 2016). "Consistently, low VEGFA and FGF2 expression correlated with better response to NAC in breast cancer patients." (PMID 27362808, 2016). "We further show that miR-205 directly binds VEGFA and FGF2 mRNA 3′-UTRs and confirm that miR-205 levels are negatively correlated with VEGFA and FGF2 mRNA expression in breast cancer patients." (PMID 27362808, 2016). "To further substantiate a link between ZEB1, VEGFA and tumor angiogenesis, we performed immunohistochemical staining for ZEB1, VEGFA, and CD31 in 228 cases of human breast carcinoma." (PMID 26882471, 2016). "Previously, we identified that key molecules (IL6, CSF2, CCL5, VEGFA, and VEGFC) secreted by tumor cells and stromal cells in basal breast cancer can promote metastasis." (PMID 26173622, 2015). "VEGFA/C and CSF2 mRNA are overexpressed in HER2 positive breast cancer, with VEGFA and CSF2 also overexpressed in basal breast cancer." (PMID 26173622, 2015). "VEGFA/C and CSF2 mRNA are overexpressed both basal and HER2+ breast cancer relative to luminal subtypes." (PMID 26173622, 2015). "Lastly, analysis of human breast cancer transcriptome databases demonstrated a significant correlation between decreased TGFBR2 and increased VEGFA gene expression similar to what was observed in the mouse models." (PMID 25280532, 2014). "It has been clearly shown that stromal fibroblasts present in invasive human breast carcinomas promote tumor growth and angiogenesis through elevated SDF-1 and vascular endothelial growth factor A (VEGF-A) secretion." (PMID 24595168, 2014). "Plasma levels of VEGFA and IL8 after surgery were significantly elevated in the breast cancer group compared to the control group (P = 0.038 and P = 0.021, respectively)." (PMID 23981902, 2013). "We also observed an increase in the expression of additional target genes of the pathway, namely, c-Jun, VEGFA and PLAUR in TN breast cancer cell lines." (PMID 24143235, 2013). "In breast cancer (bc), ACE2 has been shown to inhibit angiogenesis, a key process in tumor progression and metastasis, by suppressing the vascular endothelial growth factor A (VEGFA)/VEGFR2/ERK signaling pathway." (PMID 40145441, 2025). "Furthermore, metformin treatment suppressed angiogenesis-related gene expression by downregulating VEGFA, VEGFR2, and NRP1, which highlights its potential to target both apoptotic and angiogenic pathways in breast cancer." (PMID 40343434, 2025). "In particular, HIF-1α binds directly to the hypoxia response element (HRE) of the VEGFA promoter in mammary tumor cells, and when the HRE site was deleted from the VEGFA promoter in a luciferase reporter assay, leptin-induced luciferase signal was significantly reduced." (PMID 39439572, 2024). "In addition, it is well known that vascular endothelial growth factor A (VEGFA) protein function is critical for angiogenesis and VM formation, influencing the pathogenesis of breast cancer." (PMID 38392969, 2024).
breast cancer (continued). "Similarly, FOXO3a can also activate miR-29b-2 and miR-338 to target vascular endothelial growth factor A (VEGF-A) and nucleotide-binding oligomerization domain 1 (NRP1), respectively, to inhibit the metastasis of breast cancer." (PMID 38505423, 2024). "Experiments have shown that AA could significantly inhibit angiogenesis and vascular permeability through VEGFA/VEGFR2 signaling axis, and decrease the growth and metastasis of breast cancer." (PMID 38687357, 2024). "Despite the abundant expression of VEGFA in breast cancer tissues in our study, it lacked correlation with tumor clinicopathologic characteristics and OS." (PMID 39302921, 2024). "Regarding the regulation of β-catenin and VEGFA by miR-204, previously it was reported that miR-204 could regulates HIF1 in breast cancer cells, and lung cancer cells." (PMID 38392969, 2024). "In breast cancer xenografts mice model, SHD could inhibit AURKA and VEGFA expression and neovascularization." (PMID 38687357, 2024). "In addition, FOXO3a induces miR-29b-2 and miR-338 expression, which directly inhibits the transcription of VEGFA and NRP1 (a coreceptor of VEGFA), respectively, thereby inhibiting breast cancer metastasis." (PMID 39519130, 2024). "The results showed that five lncRNAs including HOTAIR, DANCR, PVT1, LINC00511, and NEAT1 and 16 miRNAs and five of their targets—VEGFA, BTG2, E2F3, IRAK1, and SMAD4—have significantly different expression patterns in normal individuals compared to those with breast cancer." (PMID 36726376, 2023). "Pathway analysis was performed to determine the pathways through which target genes were involved, and the results revealed that SMAD4, SDMAD7, and VEGFA through the hippo signaling pathway, the TGF-beta signaling pathway, and the cell cycle contribute to breast cancer, respectively." (PMID 36726376, 2023). "While a negative correlation between PD-L1 and VEGFA expression was reported in patients with lung cancer, a positive correlation was found in breast cancer patients." (PMID 38152616, 2023). "Moreover, dual silencing of VEGFA in cancer cells and VEGFR1 in endothelial cells significantly suppressed VM formation in breast cancer, suggesting that codelivery of multiple siRNAs is a promising strategy to improve the anti-angiogenetic effects." (PMID 37273004, 2023). "Pathway enrichment analysis revealed that the target genes of these miRNAs were markedly enriched in some cancer-related pathways, and further investigation indicated VEGFA and EZH2 were found to be the most potential target genes in the m5C regulators-related ncRNA–mRNA network in breast cancer." (PMID 35812757, 2022). "Breast cancer cells become more aggressive in the absence of Smad2 in part because Smad2 represses basal vascular endothelial growth factor A expression." (PMID 36549646, 2022). "Rab11b-as1 enhances the expression of angiogenic factors including VEGFA and ANGPTL4 in hypoxia breast cancer cells by increasing the recruitment of RNA polymerase II, promoting tumor angiogenesis and distant metastasis of breast cancer in vitro." (PMID 36226050, 2022). "Conclusively, VEGFA and EZH2 may be the most potential targets in the DNMT3B-related miRNA–mRNA network in breast cancer." (PMID 35812757, 2022). "qPCR results showed that VEGFA mRNA levels were significantly increased in breast cancer cell-injected embryos compared to embryos without injection." (PMID 35203627, 2022). "On the contrary, it was shown that VEGFA mRNA expression levels decrease after menopause in normal breast tissue but not in breast cancer lesions." (PMID 36230822, 2022). "VEGFA is also known to modulate cancer stem cell-enriched side population in breast cancer patients through non-canonical PKA/β-catenin pathway and ABCG2/ABCB1 drug efflux transporters." (PMID 35884426, 2022). "Also, ACE2 inhibits the VEGFa/VGFR2/ERK1 pathway in both lung and breast cancer cells, which reduces the angiogenic potential of the cells in both cases." (PMID 34354732, 2021).